DLAT (dihydrolipoamide S-acetyltransferase)
Diseases named in the same sentence as DLAT in open-access papers (continued):
Sharing a sentence is not in itself a finding about the gene and the disease.
tumor (continued). "In the GPL570 dataset, upregulation of LIPT1, FDX1, LIAS, DLAT, DLD, and PDHB was noted in tumor samples, while MTF1 was downregulated." (PMID 40410601, 2025). "For example, ATP7B and dihydrolipoamide S-acetyltransferase (DLAT) protein expression showed a high expression pattern in BC samples and had an impact on the tumor cell cycle." (PMID 39309446, 2024). "Importantly, in addition to its role as a metabolic carbon source, acetate reprogrammed tumor cell metabolism and promoted immune evasion through posttranslational modification of c‐Myc, which depends on the moonlighting protein acetyltransferase activity of DLAT." (PMID 39220105, 2024). "Elevated levels of genes like DLAT, FDX1, and PDHA1 correlate with poor outcomes, greater tumor aggressiveness, and immune suppression." (PMID 39867656, 2024). "Dihydrolipoamide S-acetyltransferase (DLAT), a key component of the pyruvate dehydrogenase complex (PDC), plays a critical role in regulating the energy supply of tumor cells by modulating the citric acid cycle and oxidative phosphorylation pathway." (PMID 39702350, 2024). "Therefore, DLAT might affect tumor development by regulating the repair of DNA mismatch in cancers." (PMID 39574473, 2024). "Au@MSN-Cu/PEG/DSF decreases the expression of DLAT, LIAS (Lipoic acid synthase), NPL4 and, in combination with photothermal therapy, effectively kills tumor cells and inhibits tumor growth." (PMID 38693584, 2024). "Among them, the expression levels of CDKN2A, GLS and LIPT1 were significantly upregulated whereas the expression levels of DLAT, DLD, FDX1, MTF1 was significantly downregulated in tumor samples." (PMID 37072493, 2023). "CDKN2A, GEMIN2, DLAT, and ZCRB1 were expressed at higher levels in tumors than in normal tissues, while the expression of KLF9 in tumor tissue was lower." (PMID 36909185, 2023). "Subsequently, we investigated tumor immune microenvironment and pathway activity within the high and low RiskScore groups and screened two hub genes based on this model: COX17 and DLAT." (PMID 38078879, 2023). "Nine CRGs were differentially expressed between tumor and normal tissues, among which NFE2L2, SLC31A1, FDX1, DLD, DLAT, and DLST were lowly expressed in tumor tissues, and ATP7B, CDKN2A, and GCSH were highly expressed in tumor tissues (p<0.05)." (PMID 37205181, 2023). "Of note, seven out of ten pivotal CRGs, which were identified in Science article, showed significantly altered expression patterns, with CDKN2A exhibited higher and DLAT, DLD, FDX1, LIAS, MTF1, PDHB exhibited lower expression in tumor tissues (P<0.05)." (PMID 37384293, 2023). "Compared with adjacent non-tumor tissues, CDKN2A, DLAT, and PDHA1 protein expression was upregulated in HCC tissues." (PMID 38078880, 2023). "In contrast, the expression levels of the pro-cuproptosis genes DLAT and PDHB were obviously reduced in tumor tissues as compared to normal tissues." (PMID 36947706, 2023). "Thioctyl has the ability to target DLAT, PDHA1, and PDHB, which in turn can modulate tumor progression by influencing diverse metabolic pathways." (PMID 38114959, 2023). "A heatmap showed that the levels of expression of ATP7B, DLAT, DLD, LIAS, and SLC31A1 were upregulated and the levels of expression of DBT, FDX1, and PDHB downregulated in tumor samples." (PMID 36092880, 2022). "In tumor cell-enriched region, the expression of COPS5, DLAT, DLD, FDX1, NFE2L2, PDHA1 and PDHB in the high score group is higher than that in the low score group, while the opposite is true for DLST, GCSH and LIPT2 (P <0.05)." (PMID 36618352, 2022). "We found that LIAS and CDKN2A were significantly upregulated in tumor samples, and FDX1, DLD, DLAT, PDHA1, PDHB, MTF1, and GLS were significantly downregulated in tumor samples." (PMID 36531222, 2022).
tumor (continued). "Subsequently, we detected the expression of these CRGs in tumor and normal samples and found that 6 genes, FDX1, LIAS, DLD, DLAT, PDHB and MTF1, were significantly downregulated in tumors, while 2 genes, GLS and CDKN2A, were significantly upregulated." (PMID 36246586, 2022). "Of the six cuprotosis-related genes, we found that FDX1, LIAS, DLAT, MTF1, and GLS were differentially expressed between tumor and normal tissue and were upregulated in normal tissue." (PMID 36247012, 2022). "The heatmap showed that these genes were upregulated in tumor tissue The interaction network involving these genes indicated that DLD, DLAT, and PDHB were the hub genes." (PMID 36386799, 2022). "Among them, 7 genes (DLAT, DLD, GCSH, LIAS, LIPT1, PDHA1, and PDHB) were upmodulated, whereas 3 genes (ATP7B, FDX1, and SLC31A1) were downmodulated in the tumor group in contrast with the normal group (p < 0.05)." (PMID 36046242, 2022). "The expression of MTF1, NLRP3, and SLC31A1 was positively related with ImmuneScore, StromalScore, and ESTIMATEScore in almost all types of tumor, whereas ATP7B, DLAT, DLD, LIAS, PDHA1, and PDHB were significantly negatively correlated with the scores." (PMID 36387247, 2022). "Of the six cuprotosis-related genes included in the signature, we found FDX1, LIAS, DLAT, MTF1, and GLS to be differentially expressed between tumor and normal tissues at the protein level." (PMID 36247012, 2022). "In a 4T-1 tumor-bearing BALB/c mouse model, comprehensive evaluation of targeting efficiency, antitumor efficacy, and mechanisms of action was conducted via in vivo imaging, tumor volume monitoring, immunohistochemistry (detecting FDX1 and DLAT proteins), and TUNEL staining." (PMID 41599733, 2026). "Studies reveal a close link between cuproptosis-related genes and the tumor microenvironment, where gene expressions such as SLC31A1 correlate with immune cell infiltrates, and high DLAT expression inversely relates to survival in HCC patients with high immune cell infiltration." (PMID 40276654, 2025). "While the study of it is mainly focused on tumor therapy, in the present study, two key cuproptosis-related genes, ferredoxin (FDX1) and dihydrolipoamide S-acetyltransferase (DLAT) homologs (designated as CgFDX1 and CgDLAT), were identified from Crassostrea gigas." (PMID 39936990, 2025). "Additionally, we also investigated the expression of cuproptosis‐related genes between tumour and normal samples in the TCGA ESCA cohort and found that the expression of DLAT, GLS and LIPT1 was increased in tumour samples (p < 0.05)." (PMID 38429907, 2024). "Among the four major subtypes of BC, DLAT expression is relatively higher in TNBC, suggesting that it may dominate more pronounced tumor malignancy in this subtype." (PMID 39460738, 2024). "To verify the abnormal expression of DLAT more convincingly, we detected the expression level of DLAT in tumor and adjacent nontumor tissues from 18 PAAD patients using qRT-PCR." (PMID 36975441, 2023). "We found that five cuprotosis molecules, DLAT, PDHA1, FDX1, GLS and CDKN2A, were significantly different between paired tumour and adjacent non-tumour samples from the TCGA-STAD cohort, and LIAS, DLD, DLAT and MTF1 were significantly different among the four pathologic T categories 1–4." (PMID 36895378, 2023). "The results revealed that LIAS, DLAT, PDHA1, and CDKN2A were significantly upregulated in LUAD tumors compared to normal tissues, while ATP7B, SLC31A1, FDX1, MTF1, and GLS were significantly downregulated in tumor tissues." (PMID 36983664, 2023). "In the Human Protein Atlas database, the expressions of GLS, MTF1 and PDHA1 in tumor tissues were lower compared with those in normal tissues, while the expressions of DLAT and PDHB were significantly higher in tumor tissues compared with those in normal tissues." (PMID 36620594, 2022).
tumor (continued). "Moreover, further analysis was made to investigate the mRNA expression level of CRGs between normal and CRC samples, and we found that the expressions of FDX1, DLD, DLAT, PDHB, and MTF1 were significantly decreased, whereas LIPT1, GLS, and CDKN2A were significantly upregulated in tumor samples." (PMID 37006250, 2023). "However, as the role of cuproptosis in tumor progression remains unclear, whether DLAT can also contribute to PAAD progression through its noncanonical function (mediating cuproptosis) needs to be further studied." (PMID 36975441, 2023). "We found that FDX1, LIPT1, DLAT, PDHA1, PDHB, DLST, and ATP7A were significantly differentially expressed in tumor and nontumor tissues, with the standard of p < 0.05." (PMID 36975441, 2023). "Levels of expression of the ATP7B, DLAT, and LIAS proteins were higher, whereas the levels of expression of DBT and PDHB were lower, in tumor samples than in non-tumorous kidney tissue, in accordance with the results of differential mRNA analysis." (PMID 36092880, 2022). "We found that DLD, DLAT, PDHA1, and CDKN2A were differentially expressed between normal and tumor tissues; CDKN2A was upregulated and the other genes were downregulated in the tumor tissues." (PMID 37711156, 2023). "Additionally, increased mRNA level of CDKN2A, DLAT, GLS, LIPT1, and MTF1 in tumor were observed compared to normal group." (PMID 36703728, 2022).
cancer (53 papers, 2020 to 2025). A tumor composed of atypical neoplastic, often pleomorphic cells that invade other tissues. "DLAT expression has also been identified as a prognostic factor in several cancers, where higher levels are associated with poorer survival outcomes." (PMID 38722401, 2024). "The results of our research indicated that DLAT expression was linked to TMB in 10 different cancers and MSI in 11 different cancers." (PMID 37199628, 2023). "The relationship between COX17 and DLAT and overall survival (OS) in 32 cancer patients was analyzed and found that COX17 and DLAT expression were significantly associated with OS in many cancers." (PMID 38078879, 2023). "While direct studies connecting DBT and DLAT mutations to cancer are scarce, the significant role these enzymes play in metabolic pathways suggests they could impact LUAD development and progression by causing metabolic dysregulation." (PMID 38722401, 2024). "We demonstrated that the DLAT gene was increased in most cancers, and was a risk prognostic factor." (PMID 39574473, 2024). "We conducted a GSEA analysis to identify the pathways in which DLAT may be involved, in order to better understand the potential biological processes underlying DLAT expression in different cancer tissues." (PMID 37199628, 2023). "Interestingly, we found most mutational co-occurrence in pan-cancer, such as DLAT and ATP7B mutations, whereas less mutually exclusive mutation events were observed." (PMID 36209249, 2022). "DLAT is a core enzyme of the mitochondrial pyruvate dehydrogenase complex that supports mitochondrial function as well as the Warburg effect in cancer cells." (PMID 41155419, 2025). "Our findings indicate that DLAT expression is markedly elevated in several cancers, such as HCC, CHOL, ESCA, COAD, LUAD, and LUSC, and correlates with various clinicopathological features." (PMID 40302799, 2025). "This study investigated the expression of DLAT in pan‐cancer and GC using bioinformatics and validated the upregulation of DLAT in GC using qRT‐PCR." (PMID 39031012, 2024). "Firstly, although the bioinformatic analysis has provided us with meaningful insights regarding DLAT’s role in cancer, biological experiments in vitro or in vivo are necessary to validate our findings and translate them into clinical practice." (PMID 37199628, 2023). "Through this study, the expressions of DLAT in various cancer types can be understood comprehensively." (PMID 36949759, 2023). "Nonetheless, only a few studies have reported the roles of DLAT in cancers, which prompted us to conduct further analysis." (PMID 36611155, 2023). "Meanwhile, we demonstrate that DLAT expression is correlated with TMB in 10 cancers and MSI in 11 cancers." (PMID 37199628, 2023). "The TCGA RNA-seq analysis showed that mRNA levels of DLAT were lower in cancer tissues compared with the paracancerous tissues in BRCA, COAD, HNSC, KIRC, KIRP, PPAD, READ, and THCA." (PMID 37938155, 2023). "Studies have shown that the expressions and working mechanisms of Dihydrolipoamide S-acetyltransferase (DLAT) in different cancers vary." (PMID 36949759, 2023). "Excess Cu can bind to lipoylated enzymes in mitochondria, triggering the aggregation of dihydrolipoamide S-acetyltransferase (DLAT) and causing toxicity in cancer cells." (PMID 37907972, 2023). "Our results revealed that the mRNA level of DLAT was significantly elevated in seven types of cancer, namely, CHOL, ESCA, LIHC, LUAD, LUSC, STAD, and STES, in comparison to both paracancerous and normal tissues." (PMID 37199628, 2023). "In support of this, analyses in TCGA dataset also showed that DLAT was up-regulated in NSCLC and other types of cancers and was associated with worse survival outcomes of NSCLC patients." (PMID 35869499, 2022).
cancer (continued). "Prognostic analysis for OS, DSS, and PFS revealed that hypomethylation of DLAT, FDX1, MTF1, NLRP3, and PDHA1 was associated with low survival in most cancers, whereas hypermethylation of FDX1 and PDHB was associated with low survival in UVM(P < 0.05)." (PMID 36387247, 2022). "In drug sensitivity analysis, the expression of CDKN2A, DLAT, PDHA1, and GLS was negatively associated with some or most drugs in the Cancer Therapy Response Portal database, and the expression of DLST positively correlated." (PMID 36588699, 2022). "The PDH family constitutes pyruvate dehydrogenase complex and modulates cancer cells in oxidative stress through TCA cycle, and DLAT encodes the E2 subunit of mitochondrial PDH complex." (PMID 36003780, 2022). "Increasing evidence suggests that DLAT plays a critical role in various cancers." (PMID 40302799, 2025). "Consequently, exploring the role of DLAT expression and alterations in cancers was extremely urgent." (PMID 39574473, 2024). "In conclusion, these results identified that DLAT played an oncogenic role across cancers." (PMID 39574473, 2024). "However, the detailed role of DLAT across cancers and the potential mechanism for tumorigenesis are still unclear." (PMID 39574473, 2024). "Moreover, we evaluated the differential expression of DLAT promoter methylation levels between cancers and normal tissue." (PMID 39574473, 2024). "Furthermore, DLAT expression was positively related to different immune-related genes and immune infiltrating cells in cancers such as GBM, UVM, and DLBC." (PMID 39574473, 2024). "Our study’s findings strongly suggest that DLAT may play a critical role in the tumorigenesis and progression of various cancer types." (PMID 37199628, 2023). "Moreover, DLAT expression was positively correlated with diverse immunological characteristics, such as immune cell infiltration, cancer-immunity cycle, immunotherapy-predicted pathways, and inhibitory immune checkpoints." (PMID 37330494, 2023). "We further investigated whether there existed a co-expression between DLAT and immune-related genes in a diverse array of cancers." (PMID 37199628, 2023). "Furthermore, we carried out an enrichment analysis to gain further insight into the potential biological roles of DLAT in the development and progression of cancer." (PMID 37199628, 2023). "Overall, these findings provide new insights into the potential involvement of DLAT in modulating the immune response in cancer and suggest that DLAT may be a potential target for immunotherapy." (PMID 37199628, 2023). "Our study reveals that DLAT plays an essential role in tumorigenesis and cancer immunity, which may be used to function as a prognostic biomarker and potential target for cancer immunotherapy." (PMID 37199628, 2023). "Moreover, further mechanistic studies are needed to better understand the molecular and cellular functions of DLAT in cancer." (PMID 37199628, 2023). "The correlation calculated for all paired samples (33 cancer types) revealed that of the 10 cuprotosis molecules, six (DLAT, DLD, MTF1, CDKN2A, GLS and FDX1) may be negatively regulated by many miRNAs." (PMID 36895378, 2023). "However, our findings on the oncogenic effects of DLAT in NSCLC were in agreement with the concept of Warburg effect in which cancer cells produced more lactate from pyruvate but converted less pyruvate into acetyl-CoA compared with their normal counterparts." (PMID 35869499, 2022). "DLAT may serve as a potential immunotherapeutic target for its affection to cancer cell proliferation and carbohydrate metabolism." (PMID 35720008, 2022). "In drug sensitivity analysis and immune checkpoint analysis, the results showed that CDKN2A, DLAT, PDHA1 and GLS were negatively associated with some or most drugs in the cancer therapeutic response portal database, and the expression of DLST was positively correlated." (PMID 36588699, 2022).